TRIM28 (tripartite motif containing 28)
Diseases named in the same sentence as TRIM28 in open-access papers (continued):
Sharing a sentence is not in itself a finding about the gene and the disease.
cancer (continued). "In the context of cancer, TRIM28 displays a highly nuanced and context‐dependent role, characterized by its ability to function either as a protumorigenic factor or as a tumor‐suppressive agent." (PMID 39534556, 2024). "The following are examples of different subtypes of cancer in which TRIM28 is considered to play a key role." (PMID 39100077, 2024). "The structure and functions of TRIM28, as described, play a significant role in various diseases, particularly in cancer, making its investigation both intriguing and highly relevant." (PMID 39534556, 2024). "Since studies related to cancer encompass various aspects, the relationship of each aspect with TRIM28 will be thoroughly examined." (PMID 39534556, 2024). "This review delves into TRIM28’s multifaceted roles in maintaining health, contributing to a variety of diseases, and influencing cancer progression." (PMID 39534556, 2024). "As a protumorigenic factor, TRIM28 contributes to tumor progression by supporting the maintenance of stem cell properties and promoting cellular characteristics conducive to cancer growth." (PMID 39534556, 2024). "These contrasting roles highlight the dual nature of TRIM28’s involvement in cancer, emphasizing the complexity of its function and the importance of understanding its context‐dependent effects in cancer biology." (PMID 39534556, 2024). "Collectively, TRIM28 appears to contribute to drug resistance in certain cancers and is a significant factor rendering certain anticancer drug targets unresponsive to treatment." (PMID 39534556, 2024). "Immunohistochemical analysis has unveiled elevated levels of TRIM28 in a considerable proportion of many cancers, including BC, GC, lung, and so on." (PMID 39534556, 2024). "At the same time, highlighting the critical role of TRIM28 in cancer development and treatment provides new directions for future clinical antitumor therapies." (PMID 39100077, 2024). "Recent studies suggest that TRIM28 has the ability to facilitate the infiltration of cancer cells by regulating EMT." (PMID 39534556, 2024). "Like TRIM24, TRIM28 is typically considered as an oncogene, which is expressed higher in tumor tissue when compared to adjacent healthy tissue in various cancers." (PMID 39160596, 2024). "Tripartite motif-containing 28 (TRIM28) is a well-known marker of cancer cell stemness being deeply involved in the maintenance of stem cell renewal." (PMID 39199632, 2024). "At the same time, highlighting the functional role of TRIM28 in tumor development and emphasizing its impact on cancer treatment provides a new direction for future clinical antitumor treatment." (PMID 39100077, 2024). "In cancers, TRIM28 exhibits a dual nature, functioning as both a tumor promoter and suppressor depending on the cellular context and cancer type." (PMID 39534556, 2024). "KRAB-ZFPs and TRIM28 play important roles in regulating stem cell identity, influencing cancer stem cells, and contributing to gene expression networks in the brain." (PMID 39457550, 2024). "Clearly, the interplay between TRIM28 and the metabolic status of cancer cells is intricate and requires additional investigation." (PMID 39534556, 2024). "The TRIM family of proteins, particularly TRIM28, has emerged as a pivotal regulator in the pathogenesis of cancer, influencing a multitude of cellular processes that are critical to tumor development and progression." (PMID 39534556, 2024). "Transcriptional corepressor TRIM28 (tripartite motif-containing protein 28), enriched sevenfold in cardiac aggregates after MI, was shown to regulate autophagy in cancer cells." (PMID 37922111, 2024). "Nevertheless, there are documented instances indicating a connection between the level of TRIM28 expression and cancer." (PMID 39534556, 2024). "Given its prominent role in diverse aspects of cancer and other disease development, TRIM28 represents a promising candidate for targeted therapeutic strategies." (PMID 39534556, 2024).
cancer (continued). "Another chemotype active against all 80 cancers studied targets a multi-protein complex that includes KAP1/TRIM28." (PMID 40977882, 2024). "Mechanistically, SNHG8 sponges have miR-512-5p and upregulate TRIM28, thereby exerting a cancer-promoting effect." (PMID 39100077, 2024). "The fact that both mouse and human TRIM28 proteins promote L1 retrotransposition in human cancer cells suggests some degree of evolutionary conservation in TRIM28 functioning as an activator of L1 mobilization." (PMID 37070200, 2023). "Altogether, these data indicate that TRIM28 participates in the stemness maintenance in both physiological and cancer stem cells." (PMID 37492743, 2023). "TRIM28 protein expression levels are elevated in cancers such as gastric, lung, cervical, breast and prostate cancers." (PMID 36756159, 2023). "Taken together, these results indicate that TRIM28 is carcinogenic and contributes to cancer progression." (PMID 37781084, 2023). "TRIM28, a multifunction protein, was reported to play a role in the etiology of different cancer types." (PMID 36935008, 2023). "The combination of TRIM28 targeting with anti-PD1 therapy demonstrates promising anti-tumor efficacy against NSCLC, highlighting TRIM28 as a potential therapeutic target for this cancer type." (PMID 37865804, 2023). "Unpaired two-sample t test analysis determined that de novo L1 insertions are significantly shorter in the ‘High’ TRIM28 expression group compared to the ‘Low’ TRIM28 expression group of patients in each cancer cohort." (PMID 37070200, 2023). "Next to several well-known cancer stemness facilitators, including TRIM28 or BRD4, various other BrD proteins were recently proven to sustain stem cell-like phenotype via the utilization of distinct mechanisms." (PMID 36674511, 2023). "The expression of TRIM28 in tumor tissues of 33 cancer types and the corresponding normal tissues was compared using the TIMER online network tool with data from the TCGA database." (PMID 37781084, 2023). "We revealed that TRIM28 expression was negatively associated with most of the 150 immunomodulators in BLCA and was connected to immune checkpoint (ICP) genes in cancers." (PMID 37781084, 2023). "Based on our above findings, we next analyzed the predictive role of TRIM28 in cancer patients undergoing anti-PD-1 therapy." (PMID 37865804, 2023). "In this study, we conducted a systematic pan-cancer analysis and partial experimental validation of TRIM28 as an immunological and prognostic predictor and its involvement in immunotherapy resistance." (PMID 37781084, 2023). "To investigate the role of TRIM28 in tumors, we first analyzed its expression in 33 types of cancer, which revealed a widespread overexpression of TRIM28 across cancers." (PMID 37781084, 2023). "First, while our bioinformatics analyses provided insights into TRIM28's impacts on cancer progression and immunotherapy resistance, in vitro and in vivo biological experiments were lacking." (PMID 37781084, 2023). "For 60 ICP genes, namely, 24 inhibitory and 36 stimulatory genes, a substantial correlation with TRIM28 expression was observed in various cancers, such as UVM, THYM, THCA, SKCM, LIHC, LGG, KIRP, and BRCA." (PMID 37781084, 2023). "Based on the connection between KRAB-ZFP, stemness, and cancer, we will review the available literature that points towards the potential involvement of TRIM28 and KRAB-ZFPs in CSCs phenotype." (PMID 37492743, 2023). "TRIM28 often shows abnormal gene expression in cancer, which provides the possibility to target it for anticancer therapy." (PMID 36756159, 2023). "Using the publicly available databases, we investigated the correlation of TRIM28 with PD-L1 expression in various cancer types." (PMID 37357254, 2023). "The results suggest that TRIM28 is a potentially valuable immune response indicator and a molecular biomarker for predicting the prognosis of cancer patients." (PMID 37781084, 2023).
cancer (continued). "TRIM28 can promote EMT in various types of cancer, but the specific mechanism still needs to be further explored." (PMID 36756159, 2023). "Collectively, these findings indicate that TRIM28 expression appears to exert important effects on human cancers by modulating the immune response in the TIME, but its detailed functions are still unclear." (PMID 37781084, 2023). "To investigate TRIM28 coexpression networks, we examined the potential mechanism of the TRIM28 gene in cancer tissues via the LinkedOmics database, and BLCA was chosen as an example to demonstrate the potential effect." (PMID 37781084, 2023). "This approach identified hundreds of L1 inserts in the tumor samples of ‘High’ and ‘Low’ TRIM28 groups for each of the three cancer types." (PMID 37070200, 2023). "In the present study, we thoroughly analyzed the features of TRIM28 based on a variety of cancer databases to explore the link between TRIM28 and the immune system as well as its possible contribution to immunotherapy resistance." (PMID 37781084, 2023). "In conclusion, TRIM28 plays an important role in maintaining the pluripotent state of normal and cancer stem cells by inhibiting the expression of differentiation-related genes and inducing the expression of stem cell-related markers." (PMID 36756159, 2023). "Our study highlights the multifaceted effects of TRIM28 on multiple cancers, providing a possible theoretical basis and a new target for the treatment of cancer." (PMID 37781084, 2023). "Several studies have investigated the role of Trim28- or PRC1-interacting CBX family members in cancer development and progression." (PMID 36361869, 2022). "For instance, the melanoma antigen A6 (MAGEA6)/TRIM28 complex is a cancer-specific ubiquitin ligase which targets the tumor suppressor AMP-activated protein kinase (AMPK) for degradation, thus promoting oncogenesis." (PMID 36139694, 2022). "In particular, TRIM28 exhibited upregulation in seven cancer types, and immunohistochemical results from The Human Protein Atlas (HPA) database also showed that TRIM28 has higher expression in liver related cancer tissues than in normal liver tissues." (PMID 36461099, 2022). "These regulatory axes demonstrate that TRIM28 plays a function in cancer cell proliferation and metabolism." (PMID 35743282, 2022). "Compared to normal samples, TRIM28 mRNA level is higher in blood-related cancer patients and cell lines." (PMID 35743282, 2022). "Several TRIM genes exhibited similar expression patterns in various cancer types, such as TRIM28 and TRIM59, which were extensively highly expressed in cancer." (PMID 36461099, 2022). "TRIM28 also played a role in the development of cancer by reducing autophagy or inhibiting anti-tumor immunity and immune checkpoint blockade." (PMID 36461099, 2022). "TRIM28 was significantly overexpressed in 17 cancer types, which was consistent with the observations that TRIM28 was more prone to promote tumorigenesis." (PMID 36461099, 2022). "TRIM24 and TRIM28 are generally positively associated, while TRIM33 and TRIM66 are mostly negatively associated with cancer stemness in solid tumors." (PMID 33810347, 2021). "TRIM28 is highly expressed in many malignant tumors, its high expression in ovarian cancer and cervical cancer promotes tumor invasion and metastasis." (PMID 34330324, 2021). "Our data suggest that RIPK3 activation-dependent derepression of TRIM28 in cancer cells leads to increased immunostimulatory cytokine production in the tumor microenvironment, which then contributes to robust cytotoxic anti-tumor immunity." (PMID 34419074, 2021). "In contrast to TRIM24, the expression of TRIM28 positively correlates with MYC expression in several cancer types." (PMID 33810347, 2021). "The upregulation of TRIM28 in several types of cancers has previously been demonstrated, although it was not linked with the cancer stem cell-like phenotype." (PMID 33810347, 2021).
cancer (continued). "Downregulation of TRIM28 reduces the ability of cancer stem cells to self-renew, which significantly reduces tumor growth." (PMID 33923045, 2021). "Several studies indicated a positive correlation between TRIM28 upregulation and poor cancer prognosis in specific tumor types." (PMID 34440702, 2021). "Alongside TRIM8, TRIM28 is also essential in maintaining the stem cell characteristics of cancer cells." (PMID 33923045, 2021). "This strongly supports our claim that TRIM28 is positively associated, while TRIM66 is negatively associated with cancer stemness." (PMID 33810347, 2021). "And the overexpression of TRIM28 in cancer tissues was significantly correlated with advanced TNM stages (P < 0.001)." (PMID 33817325, 2021). "The relationship between MAGE-A proteins and ubiquitination is well known; for example, MAGEA3 and MAGEA6 form an E3 ubiquitin ligase complex with TRIM28, which participates in the survival of cancer cells by degrading AMPKa1." (PMID 34202157, 2021). "We also analyzed the prognostic potential of TRIM28 in 33 different cancer types by using Gene Expression Profiling Interactive Analysis (GEPIA) to evaluate RNA sequencing data from TCGA." (PMID 33091876, 2020). "In a subset of cancers, TRIM28 ubiquitylates the AMPKα1 subunit, resulting in its proteasomal degradation and repression of autophagy." (PMID 32226386, 2020). "To further examine the prognostic potential of TRIM28 in different cancers based on Affymetrix microarrays, we used the Kaplan-Meier plotter database." (PMID 33091876, 2020). "Overexpression of TRIM28 has been observed in a number of cancers, whereby TRIM28 expression is higher in tumour tissue when compared to adjacent healthy tissue." (PMID 32731534, 2020). "Our results are in line with previous reports, suggesting that TRIM28 protein is a direct link between cancer stemness acquisition and suppression of antitumor immune response." (PMID 33076560, 2020). "MAGEA6 and TRIM28 was combined to form a cancer-specific ubiquitin ligase that inhibited AMPK signaling pathway and induced the stemness maintenance and self‐renewal of HCC stem cells." (PMID 32514252, 2020). "Accordingly, a significant elevation in TRIM28 levels has been demonstrated in different cancer tissues including those from CRC patients." (PMID 33066016, 2020). "TRIM28 maintains both normal and cancer stem cells in the pluripotent state at least partially by repressing the genes associated with differentiation and inducing expression of stemness markers." (PMID 33076560, 2020). "Recent reports imply TRIM28 engagement in cancer stem cell (CSC) maintenance, although the exact mechanism remains unresolved." (PMID 33076560, 2020). "For an overview of pleiotropic roles of TRIM28 in cancer we refer to a previously published review by our colleagues." (PMID 33066016, 2020). "TRIM28 gene is highly expressed in different cancer types, and higher expression frequently correlates with poor patient prognosis." (PMID 33076560, 2020). "To date, several possible mechanisms were suggested for TRIM28 to facilitate the acquisition of stem-cell like phenotype in distinct cancer types, and therefore to contribute to worse patient outcomes." (PMID 33076560, 2020). "To date, several studies demonstrate significant upregulation of TRIM28 expression in different cancer tissues, which correlates with worse overall patient survival, suggesting that TRIM28 supports cancer progression." (PMID 30974870, 2019). "Tripartite motif-containing protein 28 (TRIM28) has been proved to accelerate cell proliferation and metastasis in a variety of human cancers." (PMID 30484263, 2019).
cancer (continued). "As one of the evolutionarily conserved TRIM family proteins, TRIM28 has been proved to accelerate cell proliferation and metastasis in a variety of human cancers." (PMID 30484263, 2019). "The findings of this current study suggest that the aggressiveness of TRIM28 high ratio cancers is mediated through activation of tumor progression pathways in stromal compartments and cellular pro-survival pathways in tumor epithelium." (PMID 29631612, 2018). "In order to assess stromal and epithelial TRIM28 levels in this cohort, we separately scored TRIM28 in epithelial carcinoma cells and stromal fibroblasts in 19 FFPE tissues using IHC." (PMID 29631612, 2018). "The authors suggest that expression of MAGE-A3/6 in cancer cells has the ability to act as a molecular switch to convert TRIM28 from a pro-autophagy (induction of phagophore formation) to an anti-autophagy factor by targeting AMPK for degradation." (PMID 28851455, 2017). "Undoubtedly, further studies are necessary to define the exact role of multi-domain TRIM28 protein in cancer development and progression." (PMID 28851455, 2017). "In unstressed cancer cells TRIM28 represses the expression of pro-apoptotic genes: TP53AIP1, BAX, BBC3 (PUMA) and PMAIP1 (NOXA), further suggesting that TRIM28 provides survival advantage to cancer cells." (PMID 28851455, 2017). "Here, we present distinct aspects of TRIM28 involvement in regulation of cancer cell homeostasis which collectively imply pro-tumorigenic character of TRIM28." (PMID 28851455, 2017). "Clearly, TRIM28 involvement in the regulation of cancer cell metabolic state is complicated and requires further analyses." (PMID 28851455, 2017). "To date, number of studies demonstrate significant upregulation of TRIM28 expression in cancer tissues which correlates with worse overall patient survival, suggesting that TRIM28 supports cancer progression." (PMID 28851455, 2017). "Altogether, TRIM28 maintains both normal and cancer stem cells in the pluripotent state at least partially by repressing the genes associated with differentiation and inducing expression of stemness markers." (PMID 28851455, 2017). "To do so, we first conducted a Western blotting assay with the lysates of different cancer cells to identify the lines with high- and low-TRIM28 expression." (PMID 27412325, 2016). "Since the levels of TRIM28 and TWIST1 are positively correlated in cancer tissues and overexpression of TRIM28 enhances both cell migration and invasion, we want to further determine if TRIM28 functions through TWIST1." (PMID 27412325, 2016). "In normal tissues and early stage cancers, Trim28 is responsible for cell-cycle regulation through E2F transcription factors and HDACs; therefore, Trim28 shows an anti-proliferative function and acts as a tumor suppressor." (PMID 24983967, 2014). "Additionally, TRIM28 deletion alone has been shown to have a limited effect in increasing dsRNA formation in cancer cell lines, though when combined with radiation, dsRNA formation is enhanced." (PMID 41508128, 2026). "Furthermore, both TRIM24 and TRIM28 expression associated with angiogenesis signatures in tumour samples, and conditioned media from TRIM24 and TRIM28-silenced cancer cells inhibited endothelial cell proliferation and formation of vascular tube structures." (PMID 40411304, 2025). "TRIM28 is overexpressed in several cancers, including breast, lung, and CRC." (PMID 39851497, 2025). "Furthermore, a larger body of evidence indicates that TRIM28 expression positively correlates with apoptosis resistance to apoptosis across various cell types, including cancer cells." (PMID 41303350, 2025). "Moreover, TRIM28 knockdown can enhance the efficacy of chemotherapy, targeted therapy, and immunotherapy in cancer treatment." (PMID 39100077, 2024). "The proteins that interact with or target by TRIM28 in cancer‐related contexts." (PMID 39534556, 2024).